ATG7 (autophagy related 7)
Diseases named in the same sentence as ATG7 in open-access papers (continued):
Sharing a sentence is not in itself a finding about the gene and the disease.
Tinnitus (2 papers, 2023 to 2026). Tinnitus is an auditory perception that can be described as the experience of sound, in the ear or in the head, in the absence of external acoustic stimulation. "For instance, curcumin promotes the synthesis of Atg5 and Atg7, and this is postulated to underlie most of its activity in counteracting tinnitus." (PMID 38068993, 2023). "This explains why the conditional focal deletion of Atg7 produces a loss of OHC, which occurs following specific steps that mimic the neuropathology of tinnitus." (PMID 38068993, 2023). "Remarkably, experimental silencing of ATG7 reproduces all the pathological features that are reported within OHC SC in the course of degenerative tinnitus." (PMID 38068993, 2023). "Consistently, in the course of human degenerative tinnitus, the pathology of OHC in ATG7 KO mice progresses from basal to apical turns." (PMID 38068993, 2023).
varicocele (2 papers, 2022 to 2025). A condition characterized by the dilated tortuous veins of the spermatic cord with a marked left-sided predominance. "In a study of infertility mediated by varicocele, the levels of autophagy markers ATG7 and LC3 proteins in the semen of patients were significantly higher than in the semen of fertile men, suggesting that autophagy is overactivated in male infertility caused by varicocele." (PMID 40331931, 2025).
acne (1 paper, 2024). An inflammatory process of the sebaceous glands which is characterized by comedones, nodules, papules and/or pustules on the skin. "Our analysis also spotlighted several other genes implicated in acne risk, including HRH1, ATG7, and VGLL4." (PMID 39297226, 2024). "Our research, through colocalization analysis, has identified genes such as HRH1, ATG7, and VGLL4 as related to the risk of acne, but currently, the clinical applications of these genes or proteins are mainly still in the research phase." (PMID 39297226, 2024).
acoustic neuroma (1 paper, 2021). A type of benign brain tumor that begins in the Schwann cells, which produce the myelin that protects the acoustic nerve - the nerve of hearing. "Among the patients with biallelic ATG7 variants, a 71‐year‐old patient has developed an acoustic neuroma—a benign brain tumour, but longitudinal studies in other patients will provide further insight into whether this is related to ATG7 deficiency." (PMID 34725936, 2021).
Acute hepatitis (1 paper, 2016). Acute hepatic injury resulting from inflammation typically accompanied by increased serum alanine transaminase activity. "Hence our study demonstrates that atg7 deficiency augmented ConA-induced murine acute hepatitis, indicating a protective effect of Atg7 on regulating mitochondrial ROS degradation via a p38 MAPK pathway." (PMID 26939081, 2016). "Hence, this study demonstrated that atg7 knockout in mice or Atg7 knockdown in cell culture augmented ConA-induced acute hepatitis and related cellular malfunction, indicating protective effects of Atg7 on regulating mitochondrial ROS via a p38/MAPK-mediated pathway." (PMID 26939081, 2016).
age-related macular degeneration (1 paper, 2023). Age-related loss of vision in the central portion of the retina (macula), secondary to retinal degeneration. "Knockout of the Atg5 and Atg7 in mice RPE results in insufficient autophagy and age-related macular degeneration-like phenotype in aged mice." (PMID 37936170, 2023).
airway hyperresponsiveness (1 paper, 2012). "We focused on autophagy-related 5 gene (ATG5) and autophagy-related 7 gene (ATG7) because ATG5 is essential for autophagosome formation, and ATG7 has been previously shown to be associated with airway hyperresponsiveness in animal models." (PMID 22536318, 2012).
aneurysm (1 paper, 2021). Bulging or ballooning in an area of an artery secondary to arterial wall weakening. "On the other hand, mRNA expression of LC3, ATG5, Beclin-1, and ATG7 tended to increase in aneurysm samples, although in a nonsignificant manner." (PMID 34754985, 2021).
Anxiety (1 paper, 2025). Intense feelings of nervousness, tension, or panic often arise in response to interpersonal stresses. "However, Atg7 knockdown in the Fos-dependent robust activity marking ensemble promoted memory generalization, while knockdown of Atg5 or Atg7 in the Npas4-dependent robust activity marking ensemble increased anxiety levels." (PMID 40536998, 2025).
atrophic gastritis (1 paper, 2024). "The present study, for the first time, suggests that patients with the C/C genotype for the rs4684787 of ATG7 are more likely to progress to atrophic gastritis than those with the C/T or T/T genotype." (PMID 38276136, 2024).
autoimmune hepatitis (1 paper, 2016). Hepatitis caused by autoantibodies. "Given that a variety of mechanisms may be involved in the pathogenesis of autoimmune hepatitis, further studies are required to elucidate the mechanisms of atg7 deficiency relating to T cells upon ConA stimulation." (PMID 26939081, 2016). "In this study, we utilized a Cre-conditional atg7 KO mouse model to investigate the effect of autophagy in ConA-induced murine autoimmune hepatitis, explored the mechanisms and indicated possible ways to prevent or treat ConA-induced liver injury." (PMID 26939081, 2016). "In this study, using a tamoxifen-induced conditional atg7-/- mice, we investigated the role of Atg7 in the pathogenesis of ConA-induced autoimmune hepatitis." (PMID 26939081, 2016).
bladder urothelial carcinoma (1 paper, 2017). "Here we found that ATG7 expression was remarkably elevated in human bladder urothelial carcinoma and N-butyl-N-(4-hydroxybutyl)nitrosamine (BBN)-induced mouse invasive BC." (PMID 28624205, 2017).
blastoma (1 paper, 2015). A malignant neoplasm composed of undifferentiated cells. "While ATG3, ATG5, ATG7 and ATG12 are upregulated to induce autophagy in neuro-blastoma cells when G9a is inhibited." (PMID 26397365, 2015).
bone marrow failure (1 paper, 2017). "Deleting Atg7 within HSCs caused expansive myelodysplastic disease and bone marrow failure in mice, while Lyz2-cre-mediated deletion is inefficient in granulocyte precursors." (PMID 28916263, 2017).
bone osteosarcoma (1 paper, 2025). A usually aggressive malignant bone-forming mesenchymal neoplasm arising from the bone. "Furthermore, we further determine the effects of STYK1 on GSK3β sequestration in ATG7–/– human bone osteosarcoma epithelial cells (U2OS cell line)." (PMID 40588478, 2025).
brain tumor (1 paper, 2023). "To assess the autophagy signal induced by IC50 doses of TMZ and EP in U87 or U87-R brain tumor cell lines, we investigated expression of autophagy pathway genes in the ULK/BECLIN1, ATG12/ATG7, and ATG3/ LC-II/autophagasome axes." (PMID 36660193, 2023).
Cachexia (1 paper, 2011). Severe weight loss, wasting of muscle, loss of appetite, and general debility related to a chronic disease. "The expression of autophagy-related proteins Beclin-1, Atg7 and LC3B increased approximately 2-fold during the progression of cachexia in untreated mice (P<0.001)." (PMID 21949739, 2011).
Candida infection (1 paper, 2016). "Taken together, multiple studies suggested the involvement of ATG5 and ATG7 in enhancing resistance to Candida infection." (PMID 26925060, 2016).
cerebral infarction (1 paper, 2022). An ischemic condition of the brain, producing a persistent focal neurological deficit in the area of distribution of the cerebral arteries. "After 3 days of IR, the expression levels of Atg7 in the cerebral infarction penumbra had increased significantly in both young and adult rats; however, the increase was more pronounced in young rats when compared to adult rats." (PMID 36171540, 2022).
cholangiocarcinoma (1 paper, 2022). A carcinoma that arises from the intrahepatic biliary tree (intrahepatic cholangiocarcinoma) or from the junction, or adjacent to the junction, of the right and left hepatic ducts (hilar cholangiocarcinoma). "In future studies, we will investigate the precise mechanism of how ATG7 loss-of-function contributes to tumorigenesis in cholangiocarcinoma." (PMID 35725745, 2022). "Our findings indicate that germline ATG7 variants have the potential to impact autophagy function with implications for cholangiocarcinoma development." (PMID 35725745, 2022). "Further studies are needed to examine the effect of mutant ATG7 on levels of reactive oxygen species (ROS) and DNA damage, and also to determine how increased levels of p62 may be linked to cholangiocarcinoma development through the p62-KEAP1-NRF2 axis." (PMID 35725745, 2022).
chronic hepatitis B virus infection (1 paper, 2023). Chronic form of hepatitis B infection. "In PBMCs from patients with chronic hepatitis B virus infection, expression of 18 autophagy-modulating genes was downregulated including GABARAPL1, Atg7 and CTSB as well as LC3-II protein levels." (PMID 36994103, 2023).
Cirrhosis (1 paper, 2020). A chronic disorder of the liver in which liver tissue becomes scarred and is partially replaced by regenerative nodules and fibrotic tissue resulting in loss of liver function. "No cirrhosis was observed in the livers of WT and atg7+/− zebrafish at 12 and 16 month-old." (PMID 32102330, 2020).
colorectal adenoma (1 paper, 2020). An adenoma that arises from the colon or rectum. "During the colorectal adenoma-carcinoma sequence, Atg7 is embedded in carcinogenesis in two ways: At early stages, blocking Atg7 mediates a stress response comprising tumor cell growth." (PMID 32046105, 2020).
cyst (1 paper, 2025). A sac-like closed membranous structure that may be empty or contain fluid or amorphous material. "As suppressed autophagy is thought to play a mechanistic role in cyst growth in polycystic kidney disease, the original hypothesis of the present study was that aged autophagy-related 7 knockout (Atg7)−/− kidneys would become cystic." (PMID 40496859, 2025).
diffuse gastric adenocarcinoma (1 paper, 2021). An adenocarcinoma arising from the stomach. "Four DEGs including ATG10, ATG16L2, ULK4 and GABARAPL1 showed differences in diffuse gastric adenocarcinoma subgroup, while other four DEGs including ATG7 (probe 224025_s_at), GABARAPL1, WIPI2 and GABARAPL3 showed differences in gastric intestinal type adenocarcinoma subgroup." (PMID 33604190, 2021).
E. coli infection (1 paper, 2021). "For example, RNAi knockdown of autophagy components (e.g., ATG5, ATG7, and ATG12) caused an increased pathogen load and decreased survival upon E. coli infection." (PMID 34940161, 2021).
emphysema (1 paper, 2023). "Proteomics analysis indicated that autophagy could be involved in antibiotic-associated emphysema aggravation, and increased protein levels of LC3B, atg3, and atg7 were identified by Western blotting." (PMID 37779147, 2023). "SCFA administration restored emphysema development with reduced inflammatory cells, IL-6, and IFNγ and decreased LC3B, atg3, and atg7 levels." (PMID 37779147, 2023).
eosinophilia (1 paper, 2022). "We investigated the therapeutic effects of trehalose and saccharin on macrophage IL‐1β production and eosinophilia in the mouse model of ECRS with myeloid cell‐specific autophagy‐related gene 7 (Atg7) deletion." (PMID 35988262, 2022).
experimental autoimmune encephalomyelitis (1 paper, 2023). An autoimmune demyelinating disease of the central nervous system that is produced experimentally in animals by the injection of homogenized brain or spinal cord in Freund's adjuvant. "Microglial deletion of ATG7 but not ULK1 (ortholog of Atg1) leads to defective myelin degradation and impaired recovery from experimental autoimmune encephalomyelitis." (PMID 37248218, 2023).
gastroesophageal reflux disease (1 paper, 2021). A chronic disorder characterized by reflux of the gastric and/or duodenal contents into the distal esophagus. "A study performed on a pediatric patient cohort revealed upregulated ATG7 gene expression in esophageal biopsies from active EoE patients as compared with esophagus-healthy control individuals, EoE patients in remission and patients with gastroesophageal reflux disease (GERD)." (PMID 34019141, 2021).
glomerulonephritis (1 paper, 2021). A renal disorder characterized by damage in the glomeruli. "Glomerulonephritis activity score was 8.3 ± 2.8 versus 2.4 ± 1.8 for wild type and B/Atg7–/– mice, respectively." (PMID 34335611, 2021). "Autophagy deficiency in B cells abrogates pristane-induced autoantibody production and glomerulonephritis with B cell-specific knockout of Atg7." (PMID 34335611, 2021). "In contrast, IgG deposition was significantly reduced in B/Atg7–/– mice (glomerulonephritis deposition score was 2.3 ± 0.5 versus 0.8 ± 0.6 for wild type and B/Atg7–/– mice, respectively)." (PMID 34335611, 2021). "The loss of autophagy in B cells abolishes the survival of memory B cells and long-lived plasma cells, resulting in significant reduction in autoantibody production and attenuated glomerulonephritis and pulmonary inflammation in the pristane-treated B/Atg7–/– mice." (PMID 34335611, 2021).
hearing loss (1 paper, 2022). "Among these genes, ATG5, ATG7 showed the highest node scores in the mild hearing loss group, whereas MTOR, BECN1 showed the highest node scores in the severe hearing loss group." (PMID 35463035, 2022).
Hyperoxaluria (1 paper, 2019). Increased excretion of oxalates in the urine. "Furthermore, treatment with miR‐20b‐3p‐enriched exosomes from ADSCs protected EG‐induced hyperoxaluria rats, and cell experiments confirmed that co‐culture with miR‐20b‐3p‐enriched exosomes alleviated oxalate‐induced cell autophagy and the inflammatory response by inhibiting ATG7 and TLR4." (PMID 31489770, 2019).
Hypokalemia (1 paper, 2019). An abnormally decreased potassium concentration in the blood. "Notably, RAB9, which was not activated in Atg7f/f mice in response to hypokalemia, was markedly activated in Atg7 deficient mice." (PMID 30816234, 2019).
hypoxic-ischemic encephalopathy (1 paper, 2024). "In a neonatal hypoxic-ischemic encephalopathy model, intraperitoneal injection of MT (15 mg/kg) into pups 1 h before hypoxia induction upregulated the expression of NLRX1, which downregulated mTOR expression and promoted ATG7 and Beclin-1 expression to promote mitophagy and inhibit apoptosis." (PMID 38786094, 2024).
intestinal inflammation (1 paper, 2023). "We found that upon intestinal inflammation visceral adipocytes upregulate autophagy and that adipocyte‐specific loss of the autophagy gene Atg7 exacerbates inflammation." (PMID 36795015, 2023).
intestinal obstruction (1 paper, 2024). Blockage of the normal flow of the intestinal contents within the bowel. "Down-regulation of Atg1 or Atg12 promoted intestinal excretion and mitigated the intestinal obstruction, whereas down-regulation of Atg5, or Atg7 hindered the activities of eating or defecating." (PMID 38900277, 2024). "Consistently, the groups with severe intestinal obstruction in the context of trpQ78 (that is, Atg5, Atg7 RNAi) displayed more severe apoptosis, while the Atg1 and Atg12 RNAi groups, which had mitigated intestinal obstruction, had reduced apoptosis levels." (PMID 38900277, 2024).
iron deficiency (1 paper, 2021). "Moreover, we found that when compared with the wild-type plants, the atg5-1 and atg7-2 mutants showed hypersensitive phenotypes to iron-deficiency, which were reminiscent of the phenotype of FREE1 overexpression plants." (PMID 34445480, 2021). "As a consequence, the autophagy deficient mutants, atg5-1 and atg7-2, accumulate more endogenous FREE1 protein and display hypersensitivity to iron deficiency." (PMID 34445480, 2021).
Jaundice (1 paper, 2021). Yellow pigmentation of the skin due to bilirubin, which in turn is the result of increased bilirubin concentration in the bloodstream. "Unexpectedly, we observed that 40% (9 of 22 mice) of YAP-deficient mice developed jaundice within 6 to 8 weeks regardless of Atg7, Atg5, Pten, or Wwtr1 genotype." (PMID 34088666, 2021).
Kidney Cyst (1 paper, 2025). Abnormal fluid filled sac within the kidney, either acquired or congenital. "As suppressed autophagy and increased mTOR play a role in kidney cyst growth in polycystic kidney disease, our original hypothesis was that Atg7−/− kidneys would be cystic." (PMID 40496859, 2025).
laryngeal squamous cell carcinoma (1 paper, 2023). A squamous cell carcinoma that arises from the larynx. "We focus on the new prognostic and predictive factors CD44, PDL1, and ATG7 in our study of surgical samples of patients with laryngeal squamous cell carcinoma (LSCC) using tissue microarray (TMA)." (PMID 37173926, 2023). "We are going to highlight new prognostic and predictive factors, CD44, PDL1, and ATG7, in surgical samples from patients with laryngeal squamous cell carcinoma (LSCC)." (PMID 37173926, 2023). "Here, we highlight the discovery of new prognostic and predictive factors, CD44, PDL1, and ATG7, from our study of surgical samples of patients with laryngeal squamous cell carcinoma (SCC) using tissue microarray (TMA)." (PMID 37173926, 2023).
latent infection (1 paper, 2016). "Collectively, our data reveal that miR-20a is induced by mycobacterial infection, and suppresses the protein expression of ATG7 and ATG16L1, thereby inhibiting autophagic response and promoting latent infection of M. tuberculosis and survival in macrophages." (PMID 27803889, 2016). "In this study, we found that miR-20a plays a novel role in inhibiting autophagy and promoting mycobacterial latent infection in macrophages by targeting ATG7 and ATG16L1, which may provide a better understanding of M. tuberculosis latent infection." (PMID 27803889, 2016).
lysosomal storage disease (1 paper, 2023). A metabolic disorder caused by mutations in proteins critical for lysosomal function, including lysosomal enzymes, lysosomal integral membrane proteins, and proteins involved in the post-translational modification and trafficking of lysosomal proteins. "Activating ATG7 can effectively delay the pathogenesis of various diseases, including but not limited to neurodegenerative diseases, cardiovascular diseases, and lysosomal storage diseases." (PMID 37755775, 2023).
malaria (1 paper, 2025). Malaria is a serious and sometimes fatal disease caused by a parasite that commonly infects a certain type of mosquito which feeds on humans. "Finally, the essentiality of Plasmodium Atg7 during blood and liver stages holds the potential to develop a multistage drug to alleviate malaria." (PMID 39714137, 2025).
medulloblastoma (1 paper, 2022). A malignant, invasive embryonal neoplasm arising from the cerebellum. "To further assess the role of PALB2 in mitochondrial biogenesis/function and its functional relationship with ATG7 in human cells, we used CRISPR/Cas9 to knock out PALB2 and ATG7 in the DAOY medulloblastoma cells." (PMID 35404932, 2022).
metastatic melanoma (1 paper, 2021). A melanoma that has spread from its primary site to another anatomic site. "We found that ATG5 and ATG7 are downregulated in primary and metastatic melanomas as compared to benign nevi and that patients with high levels of ATG5 and ATG7 in their tumors exhibited a better overall survival." (PMID 34458153, 2021). "In addition to our previous study where we demonstrated decreased expression of Beclin-1 in metastatic melanomas, we show here that the expression of two more ATG proteins, ATG5 and ATG7, are reduced in primary and metastatic melanomas compared to benign nevi." (PMID 34458153, 2021).
mismatch repair deficiency (1 paper, 2024). "However, the role of ATG7 in the effect of immune checkpoint blockade (ICB) treatment on high microsatellite instability (MSI-H)/mismatch repair deficiency (dMMR) CRC is still poorly understood." (PMID 38627815, 2024).